CD47 (CD47 molecule)
Diseases named in the same sentence as CD47 in open-access papers (continued):
Sharing a sentence is not in itself a finding about the gene and the disease.
tumor (continued). "Our previous study has demonstrated that selective blockade of the CD47/SIRPα axis on Raji tumor cells with NI-1701 reduced tumor growth in vivo." (PMID 35538512, 2022). "This study also provides novel insight on how this CD47- SIRPα should be manipulated for tumor immunotherapy." (PMID 35511221, 2022). "Western blot analysis indicated that CD47, galectin-1, and galectin-3 were detected on both the biomimetic nanoparticles and tumor cell membrane." (PMID 36382024, 2022). "The immune checkpoint role of CD47 is being exploited in early phase clinical trials by developing dual antibodies, which will also bind to PD-L1 to increase the anti-tumor efficiency of the immune response." (PMID 35054787, 2022). "Targeting CD47 on tumor cells allows for simultaneous tumor cell opsonization when the compounds contains a functional Fc tail." (PMID 35884427, 2022). "We next assessed the functionality of STI-6643, by analyzing its ability to block the SIRPα/CD47 interaction in vitro using CD47-presenting tumor cells and recombinant human SIRPα protein." (PMID 35664753, 2022). "Pharmacological inhibition of glutaminyl cyclases that catalyze the formation of pyro-glutamate on CD47 in tumor cells, has been identified as another potential strategy." (PMID 36052078, 2022). "Different viruses have been engineered to express anti-CD47 antibodies or nanobodies to have a multifaced attack on the tumor cells." (PMID 36311790, 2022). "Simultaneously, CD47-mediated surface immobilization of DSP107 enables the delivery of the 4-1BBL:4-1BB costimulatory signal to tumor localized T cells." (PMID 35287686, 2022). "Our quantitative analyses of tumor growth with CD47 deletion together with high-resolution imaging indicates on-target phagocytosis with IgG opsonization in B16F10 tumor suppression." (PMID 35454837, 2022). "Based on this rationale, a novel BsAb (DSP107) that inhibits the CD47 signaling pathway while simultaneously stimulating anti-tumor T cell immune response has been designed." (PMID 35978372, 2022). "Cetuximab-opsonized A431 cells, as well as trastuzumab-opsonized A431 cells, demonstrated enhanced neutrophil-dependent tumor killing in response to CD47-SIRPα inhibition." (PMID 35865547, 2022). "CD47 is usually overexpressed on tumor cells, which contributes to immune evasion and makes TAMs hard to recognize and engulf tumor cells." (PMID 35672862, 2022). "Tumor cells overexpress anti‐phagocytic ligands CD47, PD‐L1 MHC‐I, and CD24, and can interact with their corresponding receptors SIRPα, PD‐1, LILRB1, and Siglec‐10 on the macrophages and send “don't eat me” signals to evade phagocytic clearance by macrophages." (PMID 37323705, 2022). "CD47 signaling in human and murine cytotoxic T cells inhibits their antigen-dependent killing of target tumor cells in vitro." (PMID 34841476, 2022). "BBA exerts a remarkable synergistic action to enhance the CD47 inhibition resultant-tumor repression by c-myc and promote the phagocytosis of macrophages." (PMID 36561763, 2022). "Some evidence supports that targeting CD47 would be sufficient for elimination of tumor cells by macrophage." (PMID 36081498, 2022). "In situ local administration of PQ912 via an injectable hydrogel down-regulated the expression of CD47 on the tumor surface and enhanced the function of antigen-presenting cells, thereby stimulating T cell-mediated antitumor immunity." (PMID 35832081, 2022). "For example, hydrogel doped with anti-CD47 antibodies can promote phagocytosis by modulating the expression of the CD47 protein on the tumor surface." (PMID 36297679, 2022). "A recent study reported that Bifidobacterium facilitates CD47-based immunotherapy through accumulation in the tumor microenvironment (TME)." (PMID 36429112, 2022). "Bioinspired hybrid nanoparticles formed by the fusion of CD47-expressing tumor exosomes and cRGD-modified liposomes (miR497/TP-HENPs) were prepared to codeliver miR497 and TP." (PMID 35078498, 2022).
tumor (continued). "In another recent glioma mouse model, CD47-checkpoint inhibition provided effective anti-tumor immunity in five aggressive pediatric brain cancers by enhancement of CD8+ T cell priming." (PMID 35418973, 2022). "Agents targeting CD47 or its ligand SIRPα have exhibited efficacy in tumor-bearing mouse models and human trials." (PMID 35837100, 2022). "SIRPα‐CD47 inhibitory checkpoint plays a crucial role in protecting healthy cells, while tumor cells can significantly upregulate their CD47 expression compared to normal cells (two to six times) to escape from the recognition and destruction by macrophages." (PMID 36257824, 2022). "Meanwhile, due to CD47-SIRPα interaction, the phagocytosis activity of tumor cells by macrophages and dendritic cells is disturbed." (PMID 37305016, 2022). "Conversely, eliminating CD47 or TSP1 in the tumor microenvironment enhances the control of tumor growth by local tumor irradiation in immune competent but not in T cell-deficient mice or following depletion of CD8 T cells." (PMID 34841476, 2022). "It was observed that the percent of these cells increased and CD47 MFI in tumor cells also increased significantly due to ablative RT (p < 0.05)." (PMID 36018888, 2022). "Cancer cells exploit this negative regulatory mechanism by overexpressing CD47 on their surface to escape immune surveillance and blockade of SIRPα/CD47 interaction is reported to enhance anti-tumor ADCP and ADCC." (PMID 36077152, 2022). "Targeting CD47/SIRPα represents a novel approach to enhance anti-tumor immunity by augmenting or reactivating critical tumor clearance mechanisms, as a key immune checkpoint in different cancers similar to that of the PD-1/PD-L1 checkpoint for solid tumors." (PMID 36080360, 2022). "Multiple tumor cells have developed the ability to evade phagocytosis by phagocytes through overexpression of the surface protein CD47, and consistent with this, high CD47 expression was observed on several carcinoma cell lines examined." (PMID 35837100, 2022). "This study evaluated the effect of single high dose radiotherapy combined with an anti-CD47 monoclonal antibody (αCD47 mAb) in CT26 tumor‐bearing BALB/c mice." (PMID 36018888, 2022). "CD47 is highly expressed on normal cells and on tumor cells, which facilitates the immune escape of tumor cells in vivo." (PMID 36382024, 2022). "The best-characterized agents are anti-CD47 antibodies, which have proven effective in inducing phagocytosis of cancer cells in vitro as well as inhibiting tumor growth in murine models of both hematologic and solid tumors." (PMID 36428745, 2022). "Tumor cells can acquire the expression of molecules with ‘don’t eat me’ function (i.e., CD47), leading to inhibition of their phagocytosis by macrophages." (PMID 36498469, 2022). "For example, CD47 is an ICP protein overexpressed on the tumor cell surface that provides a “don’t eat me” signal to phagocytic cells such as macrophages." (PMID 35189921, 2022). "In conclusion, more understanding of CD47 expression regulation is very meaningful for optimizing CD47-related tumor targeted therapeutics." (PMID 35860564, 2022). "Multiple cancer cells utilize the relationship between SIRPα and its ligand CD47 to prevent tumor cell phagocytosis." (PMID 36369063, 2022). "Since a higher proportion of CD47+ TIICs was observed in the periphery of low-grade tumors, we pursued the investigation of the tumor-immune system interaction in this tissue compartment." (PMID 36171566, 2022). "Many studies reported that tumor cells had increased expression of CD47, and this provided them with successful immune escape." (PMID 35845399, 2022). "Tumor cells express CD47, which can hinder recognition by macrophages via the CD47-signal regulatory protein α (SIRPα) signaling pathway." (PMID 36744207, 2022).
tumor (continued). "In breast cancer patients, circulating tumor cells in peripheral blood with metastasis-initiating capability when injected into mice were found to express CD44, CD47, and MET, which are all encoded by HIF target genes." (PMID 35642641, 2022). "The use of exogenous antagonists can avoid the potential side effects of anti-CD47 monoclonal antibody treatment, and only a small amount of exogenous antagonists can induce tumor regression in vivo." (PMID 34973131, 2022). "One study revealed that CSCs increased CD47 expression to avoid immune-mediated elimination during conventional anti-tumor therapy." (PMID 35860564, 2022). "In 43 patients with SGC, we were the first to investigate the CD47 expression in both tumor cells and tumor-infiltrating immune cells (TIIC) in the center and periphery of primary tumors." (PMID 36171566, 2022). "CD47 mAb can block CD47-SIRPα interactions, thus resulting in the activation of TAMs and phagocytosis of both tumor and ferumoxytol." (PMID 34976214, 2022). "Anti-CD47 mAbs block this interaction, thus facilitating the killing of tumor cells by macrophages and the cross-priming of tumor-specific cytotoxic T cells, which, in turn, activate the adaptive immune response." (PMID 35886899, 2022). "Its efficacy depends on the ability of anti-CD47 mAbs to increase the tumor cell phagocytosis and prime antitumor CD8+ T cell responses." (PMID 36171566, 2022). "Recently, a small molecule, RRx-001, was identified as a tumor targeting agent, as it also downregulates CD47 on tumor cells." (PMID 35884427, 2022). "By contrast, the glycoprotein CD47 on the tumour cell membrane, which inhibits macrophage‐mediated phagocytosis, is considered a “don't eat me” signal." (PMID 35665592, 2022). "CD47 on tumor cells can bind to its ligand, signal regulatory protein α (SIRPα), on macrophages, thereby inhibiting macrophage phagocytosis." (PMID 36274066, 2022). "IgA-mediated antibody-dependent cellular cytotoxicity (ADCC) by neutrophils outperforms IgG-mediated ADCC using this cell subset, and when combined with CD47 blockade, the anti-tumor capacity can be greatly increased using IgA antibodies." (PMID 35865547, 2022). "This exponential fits well with the total tumor burden versus the number of phagocytic macrophages (Figure 3Bii, plot), and illustrates the disproportionate potency of tumor clearance possible when CD47 disruption is combined with IgG opsonization." (PMID 35454837, 2022). "Anti-cancer treatments (e.g., immunotherapy) by intervening the binding affinity of CD47 to SIRPα contribute to the adaptive immune response and tumour cells phagocytosis." (PMID 36203878, 2022). "After the discovery of its role in tumor evasion of immune surveillance, CD47 has become a novel biomarker for cancer immunotherapy, and several anti-CD47 antibodies have been studied, including B6H12, Hu5F9-G4, and ZF1." (PMID 36291980, 2022). "Tumor size in the combined RT (16 Gy) and αCD47 (mouse anti-CD47 Ab) was significantly less compared to the control, αCD47, and RT groups 45 days after the start of the study." (PMID 36018888, 2022). "Co-culture with these cytokines at concentrations ranging from 20 ng/ml to 100 ng/ml decreased anti-tumor ADCP of various cancer cells as a direct result of increased CD47 expression." (PMID 35865547, 2022). "Since macrophages are the key regulators in both innate and adaptive antitumor immunity, blockade of CD47-SIRPα interaction facilitates tumor clearance, as well as the engulfment and presentation of tumor-specific antigen mediated by macrophages." (PMID 36080223, 2022). "Blockade of the CD47-SIRPα axis generally only enhances tumor killing in the presence of tumor-targeting antibodies." (PMID 35884427, 2022). "Blocking the CD47-SIRPa interaction promotes phagocytosis of polarized-M2 macrophages to suppress tumor progression." (PMID 35281519, 2022).
tumor (continued). "Some preclinical studies have reported radiation increased CD47 expression in TME and a combination of CD47 blocking and radiotherapy has synergistic effects on tumor growth regression." (PMID 36018888, 2022). "These include novel antibody formats designed to selectively target CD47 on tumour cells as well as tumour‐targeted bispecific antibodies with improved selectivity." (PMID 35908284, 2022). "The combination of anti-CD47 antibody (400 μg/mouse) with doxorubicin (2 mg/kg) in a mouse model was shown to significantly inhibit tumor growth." (PMID 36358792, 2022). "However, the FAO-boosted CD47 overexpression although beneficial for enhancing tumor response to targeted antibody, may cause adverse effects including raising the threshold of antibody concentration for eliminating tumor cells and exhaustion of the infiltrated immune cells." (PMID 35314680, 2022). "Following treatment with an anti-CD47 antibody, they also reported inhibition of tumor growth, sustained by enhanced pro-phagocytic signals and probably by restimulating anti-tumor T cells, as well." (PMID 35054787, 2022). "Recently, it has been demonstrated that CD47 overexpression in glioma cells helps tumor cells to escape phagocytosis and correlates with decreased overall survival." (PMID 36186781, 2022). "Given this relationship between CD47 and macrophages, many studies are now analyzing the roles of CD47 in tumor immunotherapy." (PMID 35433462, 2022). "BsAbs have been developed to circumvent this issue with reduced affinity for CD47 and high affinity to a second tumor antigen." (PMID 35454825, 2022). "For example, the humanized anti-CD47 monoclonal antibody CC-90002 enables tumor cells killed by macrophages by blocking the CD47/SIRPα interaction." (PMID 35433462, 2022). "Subsequently, SIRPα–ferritin antagonized against CD47 for further enhanced tumor-specific immunity, achieving synergistic antitumor effects." (PMID 35566065, 2022). "Currently, different agents, such as antibodies against either CD47 or SIRPα, or other therapeutic biologics directed against CD47, are being investigated for their ability to block the CD47-SIRPα axis to promote tumor reduction." (PMID 35884427, 2022). "We found that treatment with Bev (10 mg/kg) + anti-CD47 (20 mg/kg) decreased the microvessel density of xenograft tumours to 1.59 ± 0.08‰, compared to that of treatment with PBS group (7.06 ± 0.76‰)." (PMID 35694254, 2022). "We demonstrate this strategy in two different models of metastasis by CD47 deletion and by adoptive transfer of SIRPα-blocked marrow cells in combination with tumor-opsonizing IgG." (PMID 35454837, 2022). "We also found that the localization of CD47 protein was mainly the tumor cell membrane, whereas CD47 was widely distributed in the cancer tissue including on the luminal surface." (PMID 35295998, 2022). "In fact, tumor cells often overexpress CD47, thereby even more strongly restricting neutrophil-mediated tumor killing." (PMID 35884427, 2022). "Meanwhile, tumor cells in metastatic LNs also had high expression levels of CD47, and HLA-A/B/C, which is beneficial to tumor cells escaping the attack of immune cells." (PMID 36569924, 2022). "Therapeutic blockade of the CD47/SIRPα axis by small molecules or monoclonal antibodies (mAbs) is a proven strategy to enhance macrophages-mediated anti-tumor activity." (PMID 35664753, 2022). "The macrophage checkpoint interaction CD47-SIRPα is an emerging target for cancer therapy, but clinical trials of monoclonal anti-CD47 show efficacy only in liquid tumors when combined with tumor-opsonizing IgG." (PMID 35454837, 2022). "Both M1 and M2 macrophages are receptive to the action of CD47 monoclonal antibodies or SIRPα fusion proteins to exert their anti-tumor effects." (PMID 36158683, 2022). "As in the case of downmodulation by shRNA, expression of CD47 in anti-SIRPγ mAb–treated tumor cells was restored by exposure to IL-1β and GM-CSF." (PMID 35229723, 2022).
tumor (continued). "CD47 negatively regulates anti-tumor immunity by inhibiting phagocytosis, and its overexpression has been observed in most cancers." (PMID 35701829, 2022). "While the anti-LILRB2 antibody was not effective, the anti-LILRB1 antibody enhanced ADCP considerably, but strictly required simultaneous CD47 blockade and the presence of a tumor targeting CD20 antibody to become effective." (PMID 36389667, 2022). "To provide a broader view of the role of CD47 in the interplay of the tumor-immune system, we compared the proportions of CD47+ tumor cells and CD47+ TIICs in each histological subtype, and also in the central and peripheral tissue compartment." (PMID 36171566, 2022). "While the monovalent CD47 antibody arm binds CD47 and triggers strong tumor cell phagocytic activity, it has little effect on normal human CD47 single positive cells." (PMID 35978372, 2022). "CD47 on tumor cells and SIRPα on TAMs facilitate a “don't-eat-me” signal which prevents cancer cells from immune clearance." (PMID 36970051, 2022). "Membrane protein CD47 overexpressed on tumor cells engages in “don’t eat me” signal that prevents macrophages from engulfing tumor cells." (PMID 35837100, 2022). "SIRPα is expressed on monocytes, MDMs, and MDDCs where it interacts with its ligand CD47, which is expressed on most cells as a “don’t eat me” signal, but is often overexpressed by tumor cells to escape immune checkpoint." (PMID 36077152, 2022). "It was found that by blocking CD47 with anti-CD47 antibodies, the interaction between SIRPα and CD47 can be reduced, resulting in the enhancement of the ability of macrophages to present tumor cells." (PMID 36253800, 2022). "Given the crucial role of the CD47-SIRPα axis in tumor progression, we next evaluated the expression level of SIRPα in macrophages cultured with 4MU CM." (PMID 35410993, 2022). "By blocking both PD-L1 and CD47 on CTCs, the immune system can maintain a higher quality of T cells and natural killer (NK) cells to eliminate tumours." (PMID 35406441, 2022). "Now, tumor immunotherapy targeting the CD47/SIRPA axis has also become a hotspot in cancer treatment." (PMID 35211415, 2022). "For example, a phase II study in colorectal cancer patients of anti-CD47 IgG4 mAb Hu5F9-G4 in combination with Cetuximab, reported stable disease in 45% of patients, as well as increased macrophage tumour infiltration." (PMID 35020853, 2022). "Synergistic antitumour activity was observed on the basis of tumour volume, tumour weight, tumour inhibition rate, tumour angiogenesis and tumour metastasis when bevacizumab was combined with an anti-CD47 monoclonal antibody." (PMID 35694254, 2022). "Anti-CD47 therapy was shown to promote the effect of chemotherapy by inhibiting tumor proliferation." (PMID 36358792, 2022). "In the tumor center, the proportion of CD47+ tumor cells was comparable to the proportion of CD47+ TIICs in most histological subtypes." (PMID 36171566, 2022). "CD47 blockade indirectly enhances anti-tumor cytotoxicity by stimulating macrophage phagocytosis and antigen presentation by APCs, which enhances CD8+ T cell cytotoxicity." (PMID 35164813, 2022). "An EV-based immune checkpoint blockade that antagonizes the interaction between CD47 and signal regulatory protein alpha (SIRPalpha) to block the “don’t eat me” signal CD47 at the tumor site has been described." (PMID 36498469, 2022). "In vitro studies showed improved IgA-mediated ADCC by PMNs upon disruption of the CD47-SIRPα interaction in SKBR3 and A431 cells, either by blocking SIRPα or knocking out CD47 in the tumor cell line." (PMID 35865547, 2022). "Tumor cells upregulate CD47 expression to facilitate a “don't-eat-me” signal that inhibits macrophage-mediated phagocytosis of tumor cells." (PMID 36970051, 2022). "CD47 is commonly expressed on normal human cells but is found to be overexpressed on the surfaces of malignant cells from a number of tumor types, including hematologic malignancies, as well as aged erythrocytes." (PMID 35626039, 2022).